HEXA (hexosaminidase subunit alpha)
Diseases named in the same sentence as HEXA in open-access papers (continued):
Sharing a sentence is not in itself a finding about the gene and the disease.
Sandhoff disease (28 papers, 2012 to 2025). A lysosomal disorder from the GM2 gangliosidosis family, caused by biallelic pathogenic variants in the HEXB gene, characterized by GM2 ganglioside accumulation in the nervous system and progressive central nervous system degeneration. "TSD and Sandhoff disease are lysosomal storage disorders caused by mutations in the HEXA and HEXB genes, encoding the α and β subunit, respectively." (PMID 41026525, 2025). "The main forms include Tay–Sachs disease (TSD), caused by mutations in the HEXA gene, and Sandhoff disease (SD), caused by mutations in the HEXB gene." (PMID 41511290, 2025). "The GM2 gangliosidoses (GM2), Tay-Sachs and Sandhoff diseases, are rare, autosomal recessive genetic disorders caused by mutations in the lysosomal enzyme β-hexosaminidase A (HEXA) or β-hexosaminidase B (HEXB) genes, respectively." (PMID 32295606, 2020). "In this study, HexA was expressly chosen to be tested as it represents the most important isoform from the biomedical point of view, inasmuch as the HEXA gene mutation is involved in both Tay-Sachs and Sandhoff diseases, contrarily to HexB, which is only involved in Sandhoff disease." (PMID 34064736, 2021). "Specifically, mutations in the HEXA and HEXB genes lead to fatal neurodegenerative diseases: Tay–Sachs disease and Sandhoff disease, respectively." (PMID 40564923, 2025). "In the Sandhoff disease mouse model, rescue potential was severely reduced when HexA was introduced after disease onset." (PMID 39752451, 2025). "For example, several studies have demonstrated the safety and widespread distribution of HEXA in the CNS following intracranial infusion of AAVrh8 encoding HEXA and HEXB in cats with Sandhoff disease." (PMID 36835039, 2023). "Mutations in the HEXA gene lead to Tay–Sachs disease, while mutations in the HEXB gene lead to Sandhoff disease." (PMID 36835039, 2023). "In Sandhoff disease, a mutation in the HEXB gene determines the absence or abnormal functioning of the HexA enzyme." (PMID 35466219, 2022). "Intracerebroventricular (ICV) injections of a modified HexB, with both HexA and HexB activities, into Sandhoff’s disease mouse models showed marked reductions in GM2 and a two-fold increase in Hex activity, as well as an observed reduction of GM2 in the liver." (PMID 35865957, 2022). "GM2 gangliosidoses include the Tay-Sachs disease, the Sandhoff disease, and the GM2 AB, which result from LoF mutations in the genes HEXA, HEXB, and GM2A, respectively." (PMID 34690692, 2021). "HexA consists of an α- and β-subunit; a deficiency in either subunit results in Tay–Sachs Disease (TSD) or Sandhoff Disease (SD), respectively." (PMID 34201771, 2021). "These include models deficient for GBA (e.g. modeling Gaucher disease), HEXB (e.g. Sandhoff disease) or HEXA (e.g. Tay-Sachs) or GLB1 (for GM1 gangliosidosis)." (PMID 33069254, 2020). "To demonstrate that the β-hexosaminidase deficiency was responsible for the increased size of the Sandhoff disease organoids, we injected the organoids with AAV carrying monkey HEXA and HEXB genes (AAV-HEXA/B) to restore expression of β-hexosaminidase." (PMID 29358305, 2018). "Although biochemical data were suggestive of Sandhoff disease, other clinical forms of GM2 Gangliosidosis (Tay-Sachs and GM2-gangliosidosis, AB variant) were considered and HEXA and GM2A genes were analysed, excluding a potential clinical misdiagnosis." (PMID 22848519, 2012). "Hexosaminidase subunits alpha and beta (HEXA and HEXB) form a glycosyl hydrolase in lysosomes and catalyze the degradation of the ganglioside GM2, and loss-of-function mutations in these genes lead to Tay–Sachs disease (GM2-gangliosidosis type I) and Sandhoff disease (GM2-gangliosidosis type II)." (PMID 36411275, 2022).
Sandhoff disease (continued). "We also found different mutations in the HEXA and HEXB genes and that the most common mutation in HEXB was c.1597C>T, which suggests that screening the HEXB gene for this prevalent mutation is a cost-effective test in individuals with suspicion of having Sandhoff disease." (PMID 31428437, 2018). "Subsequently, AAVrh8 vectors were employed to co-deliver HEXA and HEXB in a 1:1 ratio into the thalamus and DCN, yielding prolonged survival in a Sandhoff disease feline model." (PMID 39559557, 2024). "Bilateral injection of AAV1 carrying HEXA and HEXB into the deep cerebellar nuclei (DCN) and thalamus has significantly prolonged the lifespan of Sandhoff disease mouse and feline models." (PMID 39559557, 2024). "A significant increase in HexA co-localisation with LAMP-1 was observed alongside the elevated expression of the mature form of HexA -findings shared between Tay–Sachs and Sandhoff diseases." (PMID 34831346, 2021).
lysosomal storage disorder (23 papers, 2010 to 2026). "GM2 gangliosidoses, including Tay-Sachs (TSD) and Sandhoff (SD) diseases, are lysosomal storage disorders with neurological manifestations caused by the excessive accumulation of GM2 ganglioside due to the deficiency of the β-hexosaminidase A (HexA)." (PMID 42025166, 2026). "Pseudodeficiency variants were also identified in other lysosomal storage disorders, such as p.R247W and p.R249W in the HEXA gene, p.A300T in the IDUA gene, p.R595W in the GLB1 gene, p.D152N in the GUSB gene, and p.D313Y in the GLA gene." (PMID 40449593, 2025). "It is a rare neurodegenerative lysosomal storage disorder (LSD) caused by a deficiency of ß-hexosaminidase-A (Hex-A) (HEXA; EC: 3.2.1.52) enzyme." (PMID 29973161, 2018). "Tay–Sachs disease is the second most common lysosomal storage disorder in which GM2 ganglioside accumulates in the nerve cells due to the deficiency of lysosomal β-Hexosaminidase A (HexA) enzyme." (PMID 26937414, 2015). "Tay–Sachs disease is a severe lysosomal storage disorder caused by mutations in the HEXA gene coding for α subunit of lysosomal β-Hexosaminidase A enzyme, which converts GM2 to GM3 ganglioside." (PMID 26937414, 2015). "Tay–Sachs disease is the second common lysosomal storage disorder caused by mutations in the HEXA gene." (PMID 26937414, 2015). "We previously demonstrated that AM-induced phospholipidosis is associated with the extracellular release of the lysosomal enzyme β-hexosaminidase (HexA) and that phospholipid accumulation can be measured by detecting the cell accumulation of the synthetic fluorescent lipid NDB-PC." (PMID 34884727, 2021). "A recent study that assessed the association of specific founder mutations in each of the lysosomal storage disorder genes HEXA, SMPD1 and MCOLN1, in 938 Ashkenazi Jewish (AJ) PD patients and 282 matched AJ controls, reported SMPD1 L302P as a risk factor for PD in the AJ population." (PMID 25933391, 2015). "Tay–Sachs disease (TSD) is a monogenic lysosomal storage disease (LSD) caused by mutations in the HEXA gene, which encodes the α-subunit of the lysosomal enzyme β-hexosaminidase A (HexA)." (PMID 40430919, 2025). "In the current study we performed a genetic analysis of four lysosomal storage disorder genes including GBA, HEXA, SMPD1, MCOLN1 in 231 brain autopsies from the New York Brain Bank at Columbia University." (PMID 25933391, 2015). "Finally, in addition to GRN, we found upregulation of other lysosomal genes frequently dysregulated in lysosomal storage disorders such as NEU1, NPC2, PSAP, CTSD, LAMP1, and HEXA." (PMID 38643236, 2024). "Of note, some of the lysosomal enzymes with elevated levels in MUT brain (GRN, HEXA, and GLB1 – M36) are also implicated in lysosomal storage disorders, where they generally have decreased, rather than increased, function or expression." (PMID 33749590, 2021). "This work describes a system consisting of the recombinant HexA enzyme immobilized on polylactic acid (PLA) nanoparticles (NPs), using a procedure that we have previously developed and patented, for the development of a drug-delivery system in the treatment of Sandhoff Lysosomal Storage Disease." (PMID 35466219, 2022).
GM2 gangliosidosis (19 papers, 2012 to 2026). A group of recessively inherited diseases characterized by the intralysosomal accumulation of G(M2) GANGLIOSIDE in the neuronal cells. "Our findings indicate that treatment with HexD3, a newly engineered HexA variant, is efficacious in treating the SD mouse model of GM2 gangliosidosis." (PMID 39752451, 2025). "Tay–Sachs disease (TSD) is a hereditary GM2-gangliosidosis caused by a defect in the α-subunit (HEXA gene) of β-hexosaminidase A (HexA)." (PMID 41155400, 2025). "TSD is the most common variant of GM2 gangliosidosis, with more than 100 mutations identified in the HEXA gene." (PMID 32961778, 2020). "GM2-gangliosidosis can be caused by mutations in three genes: HEXA (15th chromosome), HEXB (5th chromosome), and GM2A (5th chromosome)." (PMID 30524313, 2018). "We expected to create a severe phenotype similar to some of the available severe mouse models for GM2 gangliosidosis with HexA deficiency, i.e., SD (Hexb−/−) and double knockout TSD (Hexa−/-Neu3−/−) models." (PMID 38098938, 2023). "Whole-exome sequencing identified a homozygous HEXA gene variant of uncertain significance, without definitive biochemical or clinical evidence of GM2 gangliosidosis." (PMID 42022979, 2026). "Hence, deficiency of any of these proteins that are encoded by the HEXA, HEXB, and GM2A genes, respectively, causes excessive intra lysosomal accumulation of GM2 gangliosides and related glycolipids, especially in neuronal cells resulting in GM2 gangliosidosis." (PMID 32883051, 2020). "However, it is worth to point out that the clinical features presented by the patient are strongly suggestive of a GM2 gangliosidosis and the sequence analysis of the HEXA and GM2A genes, showing the absence of mutations enabled us to exclude other clinical forms of GM2 gangliosidosis." (PMID 22848519, 2012).
Gaucher disease (6 papers, 2014 to 2026). Gaucher disease (GD) is a lysosomal storage disorder encompassing three main forms (types 1, 2 and 3), a fetal form and a variant with cardiac involvement (Gaucher disease - ophthalmoplegia - cardiovascular calcification or Gaucher-like disease). "The inflammation markers chitotriosidase (CHIT1) and β-hexosaminidase (heterodimer or homodimer of HEXA and/or HEXB) are markedly increased in the serum of Gaucher's disease patients and used as biomarkers to monitor disease activity." (PMID 36951087, 2023).
Ataxia (4 papers, 2018 to 2024). Ataxia refers to impaired coordination of voluntary muscle movement. "In contrast to HEXA-deficient mice HEXB-deficient TSD mice, develop CNS neurodegeneration, with spasticity, muscle weakness, rigidity, tremor, and ataxia." (PMID 30524313, 2018). "HEXA/NEU3-deficient mice have progressive neurodegeneration, bone structure anomalies, and neurologic abnormalities such as ataxia, tremor and slow movement." (PMID 30524313, 2018).
diabetes (2 papers, 2020 to 2022). "We showed that the rs77768175 AA genotype, rs2074356 GG genotyp,e and rs11066280 TT genotype in HECTD4 were associated with significantly increased risks of diabetes (by 1.839, 1.746, and 1.723 in the HEXA group and by 1.719, 1.787, and 1.659 in the Ansan–Ansung group, respectively) in drinkers." (PMID 35713687, 2022). "Furthermore, we found that the rs77768175 AA genotype, rs2074356 GG genotype, and rs11066280 TT genotype in HECTD4 had increased risks of diabetes by alcohol consumption amounts (low, moderate, and high) in the HEXA group." (PMID 35713687, 2022). "Urinary excretion of CD14, HEXA, and LUM was significantly elevated in early diabetes as reported by Singh and colleagues, but was variable in the study by Suh and colleagues." (PMID 32453760, 2020).
gangliosidosis (2 papers, 2021 to 2024). A group of autosomal recessive lysosomal storage disorders marked by the accumulation of gangliosides. "In our cohort, two patients carried the missense variant c.533G > A in HEXA, a gene implicated in gangliosidosis." (PMID 34440436, 2021).
glioma (2 papers, 2020 to 2021). A benign or malignant brain and spinal cord tumor that arises from glial cells (astrocytes, oligodendrocytes, ependymal cells). "Meanwhile, other grade gliomas patients with higher expression of HEXA and HEXB mRNA expression were also predicted the lower survival probability." (PMID 34422641, 2021). "Interestingly, all WHO grades of gliomas patients with higher HEXA and HEXB expression were predicted a poor prognosis." (PMID 34422641, 2021). "Interestingly, CGGA database showed that the expression level of HEXA and HEXB was higher in the highest-grade glioma (WHO IV), than that in low-grade gliomas." (PMID 34422641, 2021).
Niemann-Pick disease type C (2 papers, 2024 to 2025). NPC is a complex lipid storage disease mainly characterized by the accumulation of unesterified cholesterol in the late endosomal/lysosomal compartment. "We generated models in HEK293T cells of known human pathogenic PTCs corresponding to a TAG stop codon in TPP1, HEXA and NPC1 genes that cause Batten disease, Tay–Sachs disease and Niemann–Pick disease type C1, respectively." (PMID 41261131, 2025).
astrocytoma (1 paper, 2025). "In the case of astrocytoma U87MG cells, gene editing with HEXA cDNA led to a significant increase in HexA activity compared to untreated cells." (PMID 40430919, 2025).
CLN6 disease (1 paper, 2021). "Collectively, these findings suggest that CALR and CTSB can be used as effective biomarkers for CLN6 disease, whereas APOE, CTSZ and HEXA might serve as effective biomarkers for multiple NCL subtypes." (PMID 34870700, 2021).
dementia (1 paper, 2023). Loss of intellectual abilities interfering with an individual's social and occupational functions. "SORL1 and HEXA were significantly associated with proxy AD/dementia when testing all pLOF and high confidence missense variants (pLOF + REVEL > 50)." (PMID 36750708, 2023). "All of these genes, except HEXA, were also significantly associated with proxy AD/dementia in a replication dataset consisting of 197,506 unrelated individuals of European ancestry included in the UKB (25,980 of which had at least one parent with AD/dementia or AD themselves)." (PMID 36750708, 2023). "However, neither HEXA nor the highlighted variant were nominally associated with proxy AD/dementia in the replication dataset, which suggests that HEXA is not a gene associated with AD/dementia." (PMID 36750708, 2023).
epilepsy (1 paper, 2022). A brain disorder characterized by episodes of abnormally increased neuronal discharge resulting in transient episodes of sensory or motor neurological dysfunction, or psychic dysfunction. "Given the functional contributions of GM2A, HEXA, and HEXB to lysosomal degradation of GM2 gangliosides, we next investigated lysosomal localization of GM2 gangliosides in GSCs in comparison with nonmalignant neural cultures from epilepsy patient surgical specimens." (PMID 35133980, 2022).
hereditary ataxia (1 paper, 2024). An instance of an atactic disorder that is caused by an inherited genomic modification in an individual. "Thus, whole-exome analysis revealed a novel mutation in the hexA gene and aided in clarifying the clinical diagnosis in a patient with hereditary ataxia of unknown etiology." (PMID 39430583, 2024).
Insulin resistance (1 paper, 2025). Increased resistance towards insulin, that is, diminished effectiveness of insulin in reducing blood glucose levels. "Increasing plasma HEXA in obese mice with insulin resistance and/or type 2 diabetes improved glycaemic control through HEXA-mediated enhancement of IGF1 signalling and glucose uptake in skeletal muscle." (PMID 40156616, 2025). "Indeed, we have recently shown that HEXA is secreted from the liver, and that circulating levels are increased in mice with insulin resistance and a mouse model of type 2 diabetes." (PMID 40156616, 2025).
Lysosomal disease (1 paper, 2020). "The extent to which mutant HEXA alleles or other genes implicated in lysosomal diseases are responsible for psychiatric disease in the general population is unknown." (PMID 33005626, 2020).
lysosomal lipid storage disorder (1 paper, 2018). An inherited metabolic disorder in which harmful amounts of lipids accumulate in cells and tissues. "GM2 gangliosides are a group of lysosomal lipid storage disorders that resulted from disease-causing mutations in three autosomal recessive genes, including hexosaminidase A (HEXA), hexosaminidase subunit beta (HEXB) and GM2 ganglioside activator (GM2A)." (PMID 31428437, 2018).
neuroblastoma (1 paper, 2025). Neuroblastoma (NB) is the most common solid, extracranial childhood tumor. "In neuroblastoma SHSY5Y cells, 7 days post transfection with the HEXA cDNA, the enzyme activity was similar to that observed in untreated cells." (PMID 40430919, 2025). "Transfection with HEXA/HEXB cDNA resulted in higher enzyme activity, especially in NIH-3T3 fibroblasts, SHSY5Y neuroblastoma, and TSD fibroblasts, compared to transfection with HEXA cDNA." (PMID 40430919, 2025).
ovarian carcinoma (1 paper, 2014). A malignant neoplasm originating from the surface ovarian epithelium. "One branch clustered eight genes (NAGA, B4GALT6, HEXA, GLB1, GBA, GLA, UGCG, HEXB) with generally comparable expression levels among the cell lines, except for the UGCG gene which was expressed at considerably higher levels in both HOSE cell lines compared with the ovarian cancer cell lines." (PMID 25294702, 2014).
Sepsis (1 paper, 2022). Sepsis is defined as life-threatening organ dysfunction caused by a dysregulated host response to infection. "This would be consistent with the elevated expression of the validated endo-lysosomal DEGs GUSB and HEXA (azurophilic granules) as well as LAIR1 (specific granules) in high-density blood neutrophils from ICU patients with sepsis." (PMID 35844509, 2022). "Any of the three and/or the pooled sepsis groups significantly differed from the ICU controls for a total of eleven genes, including higher sepsis levels for the endo-lysosomal genes DIAPH2, GUSB, HEXA, LAIR1, and SGSH." (PMID 35844509, 2022).
sialidosis (1 paper, 2021). "Human Tay-Sachs patients have mutations in the HexA gene encoding for lysosomal β-hexosaminidase A resulting in accumulation of GM2 ganglioside, while sialidosis patients have mutations in the neuraminidase 1 (NEU1) gene, leading to lysosomal storage of sialylated glycoproteins." (PMID 34156977, 2021).
type 1 diabetes (1 paper, 2020). "Increased urinary excretion of CD14 (P = 0.0057), HEXA (P < 0.0001), and lumican (P = 0.0014) was replicated in a second cohort of youths with and without type 1 diabetes." (PMID 32453760, 2020). "Interestingly, all enzymes involved in keratan sulfate degradation (ie., GALNS, GLB1, GNS, HEXA, and HEXB) were elevated in urines from youths with type 1 diabetes, compared to non-diabetic youths." (PMID 32453760, 2020).
neurodegenerative disease (6 papers, 2019 to 2025). A disorder of the central nervous system characterized by gradual and progressive loss of neural tissue and neurologic function. "GM2 gangliosidosis disorders are a group of neurodegenerative diseases that result from a functional deficiency of the enzyme β-hexosaminidase A (HexA)." (PMID 34201771, 2021).